CCDC91 (coiled-coil domain containing 91)
Description:
Involved in the regulation of membrane traffic through the trans-Golgi network (TGN). Functions in close cooperation with the GGAs in the sorting of hydrolases to lysosomes.
Synonyms: HSD8; p56; FLJ11088; DKFZp779L1558
Tractability: Antibody: UniProt places it where antibodies can reach, with high confidence. PROTAC: ubiquitination databases record sites on it; its protein half-life has been measured.
Gene: Protein-coding gene on chromosome 12 (28,133,249 to 28,581,511, forward strand). Ensembl gene ENSG00000123106.
Subcellular location: Membrane; Golgi apparatus, trans-Golgi network membrane; Golgi apparatus, trans-Golgi network
Subcellular location (Human Protein Atlas): Acrosome; Golgi apparatus; Nucleoplasm; Equatorial segment; Flagellar centriole
Gene Ontology:
Molecular function: identical protein binding
Biological process: Golgi to lysosome transport; Golgi vesicle transport
Cellular component: Golgi apparatus; membrane; trans-Golgi network; cytosol
Genetic constraint (gnomAD): Loss-of-function variants: 6 observed, 10.92 expected, observed/expected ratio (o/e) 0.55, 90% interval 0.3 to 1.08. The upper end of that interval is the gene's LOEUF score, 1.08, which puts it in group 4 of 6, group 1 being the genes least tolerant of losing a copy. Missense variants: 164 observed, 167.34 expected, observed/expected ratio (o/e) 0.98, 90% interval 0.86 to 1.12. Synonymous variants: 62 observed, 60.29 expected, observed/expected ratio (o/e) 1.03, 90% interval 0.84 to 1.27.
Homologues: Orthologues: chimpanzee CCDC91 (99% identical), macaque CCDC91 (97% identical), dog CCDC91 (94% identical), pig CCDC91 (94% identical), rabbit CCDC91 (86% identical), guinea pig CCDC91 (85% identical), mouse Ccdc91 (79% identical), rat Ccdc91 (78% identical).
Diseases named in the same sentence as CCDC91 in open-access papers:
CCDC91 is named in the same sentence as 22 diseases in open-access papers, as found by Europe PMC text mining. Sharing a sentence is not in itself a finding about the gene and the disease. The quoted sentences say what the papers report.
bipolar disorder (2 papers, 2010 to 2023). A disorder of the brain that causes unusual shifts in mood, energy, activity levels and the ability to carry out day-to-day tasks. "It has been found that many members in the same pathway of CCDC91 are associated with bipolar disorder, and its binding partner AP1G1 was up-regulated in the post-mortem cerebellum of schizophrenia patients." (PMID 20808825, 2010). "One study showed an increased incidence of copy number variation in CCDC91 in bipolar disorder patients." (PMID 37055858, 2023).
breast carcinoma (2 papers, 2013 to 2016). "Our findings also suggest a possible interrelation between PTHLH and CCDC91 in the etiology of breast cancer." (PMID 27459855, 2016). "Other coding SNPs that could include causal variants producing synthetic associations (associations of rare with common SNPs of high penetrance) include SNPs in genes INS-IGF2, ZFYVE26, C16orf46, UNC13A, NRIP1 and CCDC91 for breast cancer and SNPs in SNED1 and PASK for prostate cancer." (PMID 23555315, 2013).
schizophrenia (2 papers, 2010 to 2024). A major psychotic disorder characterized by abnormalities in the perception or expression of reality. "Further, CCDC91 (up-regulated in our analyses) has been proposed as a potential protein biomarker of schizophrenia in a recent proteome-wide association study (PWAS)." (PMID 39727940, 2024).
Azoospermia (1 paper, 2022). Absence of any measurable level of sperm,whereby spermatozoa cannot be observed even after centrifugation of the semen pellet. "Thus, the present study, in relation to the individual previous studies, aims to identify SPA17, PPP1R36, AURKA, TRIP13, PLK4, CCDC90B, and CCDC91 genes as important biomarkers of both teratozoospermia- and azoospermia-associated infertility in men." (PMID 36292606, 2022). "In the present study, we integrated four datasets, i.e., two for teratozoospermia and two for azoospermia, and successfully identified two genes, CCDC90B and CCDC91, which are commonly affected in both teratozoospermia and azoospermia." (PMID 36292606, 2022). "However, the CCDC90B and CCDC91 genes emerged as the most prominent markers common to both teratozoospermia and azoospermia as confirmed by all three analyses, i.e., Network Analyst, ExAtlas, and GEO2R." (PMID 36292606, 2022). "Therefore, it can be said that CCDC90B and CCDC91 genes could be the potential common biomarker candidates in the pathospermic conditions of both teratozoospermia and azoospermia." (PMID 36292606, 2022).
Infertility (1 paper, 2022). "However, CCDC90B and CCDC91 genes were identified as the most notable markers and they might play significant roles in the diagnosis and treatment of these two infertility conditions, paving the way to targeted therapy to cure these forms of male infertility." (PMID 36292606, 2022).
osteoarthritis (1 paper, 2026). A noninflammatory degenerative joint disease occurring chiefly in older persons, characterized by degeneration of the articular cartilage, hypertrophy of bone at the margins and changes in the synovial membrane. "CCDC91 is a known target of Runx2, and variants affecting its expression have been implicated in musculoskeletal traits such as height, estimated bone mineral density, spine bone area, neck bone area, OPLL, osteoporosis, and osteoarthritis." (PMID 41595523, 2026).
pulmonary fibrosis (1 paper, 2024). Chronic progressive interstitial lung disorder characterized by the replacement of the lung tissue by connective tissue, leading to progressive dyspnea, respiratory failure, or right heart failure. "A meta-analysis of 17 GWAS studies identified sentinel variants in or near the CCDC91 gene associated with forced vital capacity (FVC), a key criterion for the diagnosing restrictive lung diseases such as pulmonary fibrosis." (PMID 38627542, 2024).
viral infections (1 paper, 2024). "Although there is limited specific information on the expression changes of CCDC91 in response to viral infections, CCDC50, a related gene to CCDC91, negatively regulated the type I IFN signaling pathway initiated by RIG-I-like receptors (RLRs), the sensors for RNA viruses." (PMID 39066192, 2024).
cancer (4 papers, 2012 to 2023). A tumor composed of atypical neoplastic, often pleomorphic cells that invade other tissues. "We align the sequence pairs for the coding sequences of the genes of BRCA1, ELK1, and CCDC91, which are related to cancer incidence –." (PMID 35402983, 2021). "CCDC91 is also expressed in a variety of cancer cell lines including MCF7." (PMID 27459855, 2016). "Interestingly, studies in other cancers had already identified WTIP, NAP1L3, and CCDC91, as relevant genes for tumor progression." (PMID 37772256, 2023).
neurodevelopmental disorder (3 papers, 2025 to 2026). A behavioral and cognitive disorder with onset during the developmental period that involves impaired or aberrant development of intellectual, motor, or social functions. "Our findings on the genomic basis of SUD-related neurobehavioral changes also highlighted the importance of neurodevelopment, with gene CCDC91 identified to be involved in the onset of neurodevelopmental disorders." (PMID 40492099, 2025).
tumor (3 papers, 2016 to 2023). "Using data on tumor tissues from TCGA, we found that rs10843110, rs56318627 and rs11049453 within signal 3 were associated with the expression of PTHLH at P < 0.05 and CCDC91 at P < 0.10." (PMID 27459855, 2016).
CCDC91 also shares sentences with these, for which no sentence is quoted: periodontal disease (2 papers); breast tumors (1); depression (1); diffuse idiopathic skeletal hyperostosis (1); lung adenocarcinoma (1); male infertility (1); osteoporosis (1); prostate carcinoma (1); pulmonary diseases (1); restrictive lung diseases (1); teratozoospermia (1).